KRT5 (keratin 5)
Diseases named in the same sentence as KRT5 in open-access papers (continued):
Sharing a sentence is not in itself a finding about the gene and the disease.
COVID-19 (12 papers, 2020 to 2025). A disease caused by infection with severe acute respiratory syndrome coronavirus 2. "The SOX2−/TP63+ Wnt-activated transcriptional signature of KRT5−/KRT17+ basaloid cells in IPF and SOX2− signature of KRT5−/KRT17+ basaloid cells in post-COVID-19 fibrosis suggest that loss of SOX2 expression may explain the formation of these distinct dysplastic lesions in lung disease." (PMID 38182591, 2024). "However, according to scRNA-seq data, PLAU expression increased only in certain cell types (KRT17+ KRT5-) in COVID-19 patients; uPA protein accumulation may be linked to abnormal internalization and lysosomal degradation, directed by uPAR." (PMID 36674896, 2023). "Our data show that IPF and post-COVID-19 are similar in that they both exhibit KRT5−/KRT17+/SOX2− cells." (PMID 38182591, 2024). "These KRT5−/KRT17+ cells from COVID-19 patients were found to express SOX2 at a lower level than other cell types." (PMID 38182591, 2024). "In human IPF and COVID-19 damaged lungs, loss of SOX2 correlates with the appearance of aberrant KRT5−/KRT17+ epithelial cells." (PMID 38182591, 2024). "PLAU and PLAUR expression was also observed in a fraction of cells from a pro-fibrogenic KRT17+ KRT5- population in COVID-19 and PF patients, though the overall number of PLAU+ and PLAUR+ cells in this population was still low (median normalized expression 0)." (PMID 36674896, 2023). "In COVID-19 patients, the most prominent airway progenitors supporting alveolar regeneration were reported to be CK5+ basal cells, which form the so-called “keratin 5 pods”." (PMID 37277327, 2023). "The multiple extensive clinical interventions, treatments, and prolonged COVID-19 disease course may have induced the Krt5+ cell proliferation observed in their study." (PMID 38092883, 2023). "Public single-cell RNA-Seq data of nine patients with COVID-19 revealed that in severe cases, cell clusters of lung progenitors contain a high number of KRT5-positive cells, which help establish the epithelial barrier to prevent leucocyte-mediated cytotoxicity." (PMID 35252273, 2022). "While Krt5+ cells have been identified in scRNA-seq data sets and pathology specimens from patients with severe COVID-19, more work is needed to determine whether our current understanding of the dysplastic epithelial response to injury is generalizable between different types of viral injury." (PMID 36270292, 2023). "Using lung sections from COVID-19 patients, we observed CD8+ T cells appearing in the KRT5+ lung area and p-SRC and nuclear YAP expression in KRT5+ cells." (PMID 39352385, 2024).
invasive carcinoma (12 papers, 2008 to 2024). A carcinoma that is not confined to the epithelium, and has spread to the surrounding stroma. "By 21 days p.i., primary tumors progressed to invasive carcinoma, characterized by tumor cells that were breaking through the ductal epithelial barrier as shown by cytokeratin 5 stainings, in order to invade the mammary fat pad." (PMID 33731699, 2021).
bladder tumors (11 papers, 2018 to 2026). "Interestingly, basal bladder tumors express high levels of genes typical of more undifferentiated urothelial basal cells (KRT5, KRT6, and KRT14) together with several transcription factors that support stem cell homeostasis and cancer progression also presented a CD44shigh phenotype." (PMID 35547758, 2022).
epidermolysis bullosa (10 papers, 2013 to 2024). Epidermolysis bullosa (EB) is a group of genetic skin diseases that cause the skin to blister very easily. "Wang R., Sun L., Habulieti X., Liu J., Guo K., Yang X., Ma D.,Zhang X. Novel variants in LAMA3 and COL7A1 and recurrentvariant in KRT5 underlying epidermolysis bullosa in five Chinesefamilies." (PMID 36923479, 2023). "Clinicopathological and genetic findings were consistent with the diagnosis of KRT5-related EBS providing the second example of a spontaneous mutation causing epidermolysis bullosa in cattle." (PMID 33135329, 2020). "Many promising results have been published using the CRISPR/Cas9 technology to efficiently correct mutations in epidermolysis bullosa, especially for mutations in COL7A1, COL17A1, KRT5 and KRT14." (PMID 36901775, 2023). "Vahidnezhad H., Youssefian L., Saeidian A.H., Mozafari N., BarzegarM., Sotoudeh S., Daneshpazhooh M., Isaian A., Zeinali S.,Uitto J. KRT5 and KRT14 mutations in epidermolysis bullosa simplexwith phenotypic heterogeneity, and evidence of semidominantinheritance in a multiplex family." (PMID 36923479, 2023). "For example, mutations in KRT5 and KRT14 can cause epidermolysis bullosa to a large extent." (PMID 30781701, 2019). "Urethral stenosis with secondary urinary tract obstruction can occur in epidermolysis bullosa but primary ureteric disease has not been reported in individuals with KRT5 mutations." (PMID 24260555, 2013).
lymph node metastasis (10 papers, 2007 to 2024). "KRT5 Keratin, type II cytoskeletal 5 was found decreased in primary early-stage cervical squamous cell cancer tissue with pelvic lymph node metastasis (PLNM) vs without PLNM using DIGE-based proteomics." (PMID 27601940, 2016).
viral infection (10 papers, 2011 to 2024). "The causative effect of these genes and pathways on Krt5+ “pod” induction and lung repair in viral infection-mediated chronic pulmonary injury remains elusive." (PMID 38092883, 2023). "Our findings reveal that a viral infection–induced inflammatory niche is critical for the robust expansion of KRT5+ dysplastic cells." (PMID 39352385, 2024). "Costaining for markers of immune cells with dysplastic KRT5+ cells revealed that CD8+ T cells, the major source of IFN-γ during viral infection, were recruited to injured alveoli areas, including KRT5+ pods." (PMID 39352385, 2024). "Inhibiting YAP during viral infection prevented dysplastic cell formation, whereas inhibiting YAP in persistent KRT5+ cells led to their conversion into distal club cells." (PMID 39352385, 2024). "This led us to postulate that we indeed labeled a progenitor cell population that transiently expressed p63 but not Krt5 following viral infection." (PMID 36129169, 2022). "We also injected Tmx into KRT5-CreERT2;R26Ai14 mice after viral infection and did not observe contribution of lineage labeled cells to alveolar epithelium (data not shown)." (PMID 36129169, 2022). "Intriguingly, when tamoxifen was administrated post-viral infection, Trp63CreERT2 but not KRT5-CreERT2 labels islands of alveolar epithelial cells that are negative for EBC biomarkers." (PMID 36129169, 2022). "Consistently, KRT5-CreERT2 lineage labeled cells did not contribute to AT1 or AT2 cells no matter Tmx was administered before or after viral infection (data not shown), which is in line with previous studies." (PMID 36129169, 2022). "However, we did not observe KRT5-CreERT2 lineage-labeled alveolar epithelium no matter Tmx is injected before or after viral infection." (PMID 36129169, 2022).
epithelioid mesothelioma (9 papers, 2008 to 2026). "In our first case of epithelioid mesothelioma, the neoplastic cells showed cytokeratin 5/6 (CK5/6), calretinin, and Wilms‐tumor‐1 (WT1) expression, while remaining negative with thyroid transcription factor‐1 (TTF‐1)." (PMID 36808895, 2023). "The immunocytochemical staining was performed to confirm the expression of Calretinin, Cytokeratin 5/6, WT-1, and Ki-67 were positive, which were consistent with the cytological characteristics of epithelioid mesothelioma." (PMID 33365269, 2020).
idiopathic pulmonary fibrosis (9 papers, 2016 to 2025). Idiopathic pulmonary fibrosis (IPF) is a nonneoplastic pulmonary disease that is characterized by the formation of scar tissue within the lungs in the absence of any known cause. "Indeed, in the context of idiopathic pulmonary fibrosis (IPF) our recent data showed that KRT5+ basal cells not only migrate through the fibrotic lung but that their behavior and function were impacted by the ECM microenvironment." (PMID 39991870, 2025). "Increased KRT5 and KRT14 expression has also been reported in the alveolar regions in idiopathic pulmonary fibrosis (IPF)." (PMID 27423691, 2016).
prostate tumors (9 papers, 2007 to 2024). "In contrast, expression of basal markers (TP63, KRT5) was significantly increased in the ‘low’ NKX3.1 prostate tumors." (PMID 30266798, 2018). "In particular, we found primarily overexpression of CTNNB1, CDH1, SMAD2, SMAD3, TCF3, LEF1 in younger patients and overexpression of SNAI1 and underexpression of KRT5, KRT19, OCLN, CDH2 and MUC1 which clearly indicates different characteristics of prostate tumor in younger vs older patients." (PMID 29206234, 2017).
sarcomatoid carcinoma (9 papers, 2011 to 2025). A malignant epithelial neoplasm characterized by the presence of spindle cells and anaplastic morphologic features.
metastatic tumors (8 papers, 2007 to 2025). "Cytokeratins 5 and 15 (KRT5/KRT15), markers of basal cells in prostate glands, show uniform downregulation in all metastatic tumors, confirming the absence of basal epithelial cells." (PMID 17430594, 2007).
non-small cell lung carcinoma (8 papers, 2013 to 2025). A group of at least three distinct histological types of lung cancer, including non-small cell squamous cell carcinoma, adenocarcinoma, and large cell carcinoma. "Interestingly, the SHH-induced transcription factor GLI1, which is known for its involvement in stem cell renewal in non-small cell lung cancer, localized to the nuclei of most KRT5+ cells in the distal IPF lung, arguing for activation of the SHH pathway in these cells." (PMID 27423691, 2016). "Further, PDX tissue sections generally did not express antigens characteristic of non-small cell lung cancers, including Keratin 5, Keratin 6, Keratin 7, Keratin 14, Keratin 20, TTF1, TP63, and Napsin A." (PMID 25955027, 2015).
ductal breast carcinoma (7 papers, 2007 to 2024). "In our main HER2+ ductal breast carcinoma 3D model, we observed a panCK+ luminal region and a patchy and discontinuous pattern of cytokeratin 5 (CK5) in the basal layer, although SMA, another basal marker, had uniform expression." (PMID 35121992, 2022). "Seven differentially expressed genes (KRT5, KRT6 and KRT17 between tumor and normal cells, CDH1, EMP1, DDR1 and DVL1 between lobular and ductal carcinomas) were verified by immunohistochemical detection of proteins on TMA slides comprising of cores from 119 cases." (PMID 17389037, 2007).
lung disease (6 papers, 2018 to 2025). "Our analysis revealed CLAD-specific cellular subsets including Fibro.AT2 cells, exhausted CD8+ T cells, and superactivated macrophages while suggesting that pathogenic keratin 17–positive, keratin 5–negative (KRT17+KRT5−) cells represent a common fibrotic mechanism across fibrotic lung diseases." (PMID 41122970, 2025). "Further investigation into what causes the dysplastic nature of KRT5−/KRT17+ cell state could lead to new approaches for treating lung disease." (PMID 38182591, 2024). "We only observed SOX2+/p63+/KRT5+ cells in aged individuals with pulmonary disease and dysplastic airway-like structures." (PMID 37191411, 2023). "In the exchange zone, we detected SOX2+, p63+, and KRT5+ cells in aged individuals diagnosed with lung disease." (PMID 37191411, 2023).
serous ovarian carcinoma (6 papers, 2016 to 2026). "For example, KRT5 in serous ovarian cancer was associated with chemotherapy resistance and cancer recurrence." (PMID 35302673, 2022). "In conclusion, this study found for the first time that serous ovarian carcinomas with increased KRT5 and KRT6 mRNA expression, as well as increased K5 or K5/6 immunostaining have an increased risk of disease relapse." (PMID 28147318, 2017). "This study investigated the clinical significance of keratin 5 and 6 expression in serous ovarian cancer progression and chemotherapy resistance." (PMID 28147318, 2017). "We therefore investigated the prognostic significance of KRT5 and KRT6 mRNA expression in publically available serous ovarian cancer data sets." (PMID 28147318, 2017). "Furthermore, KRT5 and KRT6C mRNA expression was assessed in chemotherapy sensitive and chemotherapy resistant primary serous ovarian cancer cells derived from patient ascites." (PMID 28147318, 2017). "KRT5 but not KRT6C mRNA expression was increased in chemotherapy resistant primary serous ovarian cancer cells compared to chemotherapy sensitive cells." (PMID 28147318, 2017).
brain tumors (5 papers, 2006 to 2022). "The overexpression of the krasG12V gene driven by cytokeratin 5 (krt5) or glial fibrillary acidic protein promoter induced brain tumor." (PMID 26572230, 2015). "From the observation of a limited number of brain tumors, it appeared that krt5-derived tumors mostly originated from VZ, while gfap-derived tumors may have originated from both the VZ and brain parenchyma." (PMID 25644510, 2015). "The low frequency of brain tumors from the krt5 gene promoter prompted us to test whether the well-characterized, broadly-expressing promoter of zebrafish radial glia gene gfap could induce higher tumor incidence." (PMID 25644510, 2015). "We found that both krt5- and gfap-derived brain tumors showed prominent phospho-ERK1/2 expression." (PMID 25644510, 2015). "When expressed under the control of the krt5 gene promoter, KRASG12V induced brain tumors in ventricular zones (VZ) at low frequency." (PMID 25644510, 2015). "To evaluate whether zebrafish could be used as a brain tumor model, we expressed the human version of KRASG12V driven by the zebrafish krt5 promoter that we recently identified and also by the well-characterized gfap gene promoter." (PMID 25644510, 2015). "Doxycycline-inducible expression of oncogenic KRAS in brain cells under the control of the krt5 and gfap gene promoters using the TetOn system (Tg(TRE:mCherry-KRASG12V; krt5/gfap:rtTa)) led to the development of malignant tumors in the cranial cavity and parenchymal brain tumors, respectively." (PMID 35565373, 2022).
cervical carcinoma (5 papers, 2016 to 2026). A carcinoma arising from either the exocervical squamous epithelium or the endocervical glandular epithelium. "In summary, the majority of cervical cancers can be divided into two groups on the basis of molecular signatures: SCCs most probably originate from the KRT5+ squamous lineage of the ectocervix, whereas ADCs most probably originate from the KRT7+KRT8+ columnar lineage of the endocervix." (PMID 33462395, 2021). "Additional DEGs that were overexpressed in cluster 8 included several known canonical cervical cancer oncogenes – CDKN2A, SERPINB3, TP63, and KRT5." (PMID 41362277, 2026). "Our results suggest that this preventive ablation alone may not eliminate potential cervical cancer precursors, as new SCJs can develop upon activation of quiescent KRT5+ stem cells, which could present target sites for HPV infection and carcinogenesis." (PMID 33462395, 2021).
cyst (5 papers, 2017 to 2023). A sac-like closed membranous structure that may be empty or contain fluid or amorphous material. "Nrf2 activation in keratin 5 (K5)-positive skin epithelia leads to hair loss, infundibula dilatation, sebaceous gland enlargement, and cyst formation, with upregulation of Epigen, Slpi, and Sprr2d in the cyst." (PMID 33511139, 2020). "The cysts in the cKO skin were filled with KRT5, and its staining in the skin was diffused in the epidermis and cyst edge, whereas in the controls, the staining was specific to the epidermal basal cells and to the HF." (PMID 35247391, 2022). "The aberrant surface phenotype of the thymic epithelium is magnified in Foxn1+/−;Foxn1:Noggin mice, in which the thymus consists of a large cyst; keratin 5-positive epithelial cells occupy a basal location and only few, if any, haematopoietic cells are present." (PMID 28819138, 2017). "The cyst epithelia stained intensely positive for human bone marrow endothelial marker-1 (HBME-1) and cytokeratin 5/6, and negative for paired box protein 8 (PAX8) and GATA binding protein 3 (GATA3)." (PMID 36862889, 2023).
dermatitis (5 papers, 2009 to 2024). An inflammatory process affecting the skin. "For example, the G > A transition variant in position-1 of intron 7 was used as an alternate acceptor splice site and led to the retention of intron 7 in the transcript of the keratin 5 (KRT5) gene, which directly downregulated KRT5 expression in a heritable skin disorder." (PMID 39408729, 2024).
metastatic melanoma (5 papers, 2018 to 2024). A melanoma that has spread from its primary site to another anatomic site. "In the present study, we demonstrated that the expression of KRT5 was lower in metastatic melanoma than in primary melanoma, and this expression was markedly correlated with tumor stage and T stage in patients with SKCM." (PMID 33441834, 2021). "Our study found that genes involved in the biological processes of desmosome organization (GO: 0002934) and hemidesmosome assembly (GO: 00031581) in metastatic melanomas, including JUP, PKP3, KRT14, and KRT5, were inhibited." (PMID 29377892, 2018).
adenoid cystic carcinoma (4 papers, 2007 to 2024). A malignant tumor arising from the epithelial cells. "All 4 adenoid cystic carcinomas cluster together in branch III and 5/7 of the apocrine tumors cluster together in branch V. All 18 tumors in branch II are positive for KRT5/6 staining, 97% of the tumors in branch I are EGFR negative, and all 14 tumors in branch V are KIT negative." (PMID 17910759, 2007).
adenoma (4 papers, 2017 to 2024). A neoplasm arising from the epithelium. "In the LNM-positive group compared to the control adenoma, there were significant increases in gene expression for CCL15, SSX1, and KRT5 genes, alongside significant decreases in HLA-E, ITPK1, ANXA1, and TXNIP genes across the head, proximal stalk, and distal stalk regions." (PMID 38256174, 2024).
fibrosis (4 papers, 2019 to 2024). the formation of excess fibrous connective tissue in an organ or tissue in a reparative or reactive process. "Specifically, we used mRNA expression of Krt8 (indicative of injury/repair), Krt5 (related to dysfunctional repair), Adamts4 (associated with fibrosis), and Itga5 (indicative of damage-responsive fibroblasts)." (PMID 39340037, 2024). "Although the endogenous KRT5+P63+ cells could be found in broader regions of the alveolar space as time went on, their number was still less and not enough to inhibit the progression of bleomycin-induced fibrosis." (PMID 31159891, 2019).
Hyperkeratosis (4 papers, 2014 to 2025). Hyperkeratosis is a histopathological term defining a thickened stratum corneum and may be present in many different skin conditions, with many possible overlaps. "Given the hyperkeratosis observed in VDR-KO rats through HE staining, we conducted Western blotting using the antibody against the keratin marker Krt14 and anti-pan-keratin antibody (PCK26), which detects rat keratin 1 (66 kDa), keratin 5 (58 kDa), and keratin 8 (52 kDa)." (PMID 39796272, 2025).
asthma (3 papers, 2018 to 2025). "In asthma, the airway epithelium is less differentiated, with more cytokeratin-5 positive BCs and increased p38 MAPK phosphorylation." (PMID 41303221, 2025). "Further analysis of KRT5 expression, across the three groups, showed that this gene was significantly upregulated in severe asthma compared with control and moderate asthma cases." (PMID 35222024, 2022).